SH3YL1 (SH3 and SYLF domain containing 1)
Synonyms: Ray; DKFZP586F1318
Tractability: No criterion of Open Targets' tractability assessment is met for any kind of drug.
Gene: Protein-coding gene on chromosome 2 (217,730 to 266,398, reverse strand). Ensembl gene ENSG00000035115.
Subcellular location (Human Protein Atlas): Nucleoplasm
Gene Ontology:
Molecular function: phosphatase binding; phosphatidylinositol binding; protein binding
Biological process: regulation of ruffle assembly
Cellular component: ruffle membrane
Genetic constraint (gnomAD): Loss-of-function variants: 25 observed, 27.18 expected, observed/expected ratio (o/e) 0.92, 90% interval 0.67 to 1.28. The upper end of that interval is the gene's LOEUF score, 1.28, which puts it in group 5 of 6, group 1 being the genes least tolerant of losing a copy. Missense variants: 293 observed, 308.74 expected, observed/expected ratio (o/e) 0.95, 90% interval 0.86 to 1.04. Synonymous variants: 115 observed, 118.59 expected, observed/expected ratio (o/e) 0.97, 90% interval 0.83 to 1.13.
Homologues: Orthologues: chimpanzee SH3YL1 (99% identical), macaque SH3YL1 (99% identical), pig SH3YL1 (94% identical), rat Sh3yl1 (93% identical), mouse Sh3yl1 (92% identical), guinea pig SH3YL1 (91% identical), dog SH3YL1 (90% identical), tropical clawed frog sh3yl1 (75% identical), zebrafish sh3yl1 (65% identical).
Diseases named in the same sentence as SH3YL1 in open-access papers:
SH3YL1 is named in the same sentence as 23 diseases in open-access papers, as found by Europe PMC text mining. Sharing a sentence is not in itself a finding about the gene and the disease. The quoted sentences say what the papers report.
acute kidney injury (3 papers, 2023 to 2024). Sudden and sustained deterioration of the kidney function characterized by decreased glomerular filtration rate, increased serum creatinine or oliguria. "SH3YL1 protein plays a crucial role in mediating oxidative stress pathways leading to acute kidney injury and serves as a predictive biomarker for renal outcomes in type 2 diabetes patients." (PMID 38892221, 2024). "Specifically, murine knock-out models of Sh3yl1 show reduced inflammatory response, tubular apoptosis, renal failure, and mortality after endotoxin exposure." (PMID 37365616, 2023).
type 2 diabetes (3 papers, 2023 to 2024). "The SH3YL1 gene has recently been implicated as a biomarker for nephropathy in type 2 diabetes, whereas ALKAL2 enables protein tyrosine kinase activity." (PMID 36975205, 2023). "This study presents the clinical significance of SH3YL1 as a diagnostic biomarker of renal outcomes in patients with type 2 diabetes." (PMID 37109492, 2023). "This study suggests that SH3YL1 is a new diagnostic biomarker for renal outcomes in patients with type 2 diabetes." (PMID 37109492, 2023). "Furthermore, plasma SH3YL1 levels were also increased in patients with type 2 diabetes, with a significant trend according to the albuminuric state." (PMID 37109492, 2023). "Here, we tested whether the SH3YL1 protein could predict 3-year renal outcomes in patients with type 2 diabetes." (PMID 37109492, 2023). "In this study, we tested whether the SH3YL1 protein could predict 3-year renal outcomes in patients with type 2 diabetes." (PMID 37109492, 2023). "The current study examined whether SH3YL1 was a predictive marker in patients with type 2 diabetes, showing that the USCR was a significant marker for predicting 3-year renal outcomes." (PMID 37109492, 2023).
diabetic nephropathy (2 papers, 2023). "Pathogenic conditions associated with aberrant expression of KDM6A, ANXA11 and SH3YL1 include pediatric cancer, ALS and diabetic nephropathy, respectively." (PMID 37026480, 2023).
multiple sclerosis (2 papers, 2019 to 2021). A progressive autoimmune disorder affecting the central nervous system resulting in demyelination. "As proven by recent studies, SH3YL1 expression can affect T cell activation in multiple sclerosis patients." (PMID 35004856, 2021).
bipolar disorder (1 paper, 2020). A disorder of the brain that causes unusual shifts in mood, energy, activity levels and the ability to carry out day-to-day tasks. "Among possible targets of these eRNA candidates are ARHGEF38 and SH3YL1, which have been linked to bipolar disorder and suicide, GLRA1 and MCTP2 were found to be associated with schizophrenia, and CHIR-B3, MHCIA7, MHCIY as well as MICA are genes involved in the immune system." (PMID 32854615, 2020).
bladder cancer (1 paper, 2025). "Kaplan–Meier survival analysis using The Cancer Genome Atlas bladder cancer (TCGA-BLCA) data further demonstrated that low SH3YL1 expression is significantly associated with poor overall and disease-specific survival in MIBC patients, reinforcing its role as a prognostic biomarker." (PMID 40362200, 2025). "The apparent independence of cisplatin-induced AKI from SH3YL1 expression in MIBC further raises important questions about the unique nephrotoxic mechanisms within the MIBC subset of bladder cancer patients." (PMID 40362200, 2025). "This study aims to explore the expression patterns of SH3YL1 in bladder cancer, with a particular focus on its correlation with NOX4, a gene associated with oxidative stress and implicated in cancer progression." (PMID 40362200, 2025). "To evaluate the potential of SH3YL1 and NOX4 as diagnostic biomarkers for bladder cancer subtypes, we conducted ROC (Receiver Operating Characteristic) curve analysis on SH3YL1, NOX4, and the combined SH3YL1 + NOX4 expression levels in NMIBC and MIBC groups." (PMID 40362200, 2025). "To investigate the potential role of SH3YL1 in oxidative stress regulation during bladder cancer progression, we focused on NADPH-related genes from the SH3YL1 interaction network identified in STRING." (PMID 40362200, 2025). "While many studies have actively explored the link between SH3YL1 and kidney injury, its expression and functional role in bladder cancer—particularly under cisplatin treatment—remain largely unexplored." (PMID 40362200, 2025). "By investigating these patterns, this study seeks to clarify whether SH3YL1 can serve as a reliable biomarker for both kidney injury and bladder cancer progression, specifically in the context of cisplatin therapy." (PMID 40362200, 2025). "This study investigates SH3YL1 as a potential biomarker for bladder cancer progression and AKI." (PMID 40362200, 2025). "Given cisplatin’s dual impact as both an antitumor agent and a nephrotoxin, understanding SH3YL1’s behavior in bladder cancer patients undergoing cisplatin therapy could reveal its potential as a biomarker for both tumor progression and renal injury." (PMID 40362200, 2025). "Recently, SH3YL1 has emerged as a potential biomarker for AKI, particularly in contexts associated with increased oxidative stress, sparking interest in its expression dynamics in bladder cancer patients receiving cisplatin therapy." (PMID 40362200, 2025). "The lower predictive values in NMIBC also highlight the specificity of SH3YL1 and NOX4 as potential markers for more invasive forms of bladder cancer." (PMID 40362200, 2025). "This lack of variation led us to examine SH3YL1’s role in bladder cancer progression, focusing on its associations with key oxidative stress-related genes such as NOX4 across bladder cancer subtypes." (PMID 40362200, 2025). "This specificity in MIBC underscores the potential of SH3YL1 and NOX4 to identify patients who may benefit from intensified therapeutic interventions, paving the way for more personalized bladder cancer management strategies." (PMID 40362200, 2025). "However, initial observations suggest that SH3YL1 levels do not change significantly in blood and urine following cisplatin administration in bladder cancer patients, raising questions about its applicability as a universal AKI marker in this setting." (PMID 40362200, 2025). "Plasma and urine SH3YL1 levels were measured in bladder cancer patients undergoing cisplatin treatment, showing elevated baseline levels compared to controls, suggesting a link with bladder cancer pathology rather than cisplatin-induced AKI." (PMID 40362200, 2025). "Our analysis of SH3YL1 expression in blood and urine samples of bladder cancer patients receiving cisplatin therapy revealed no significant changes post-treatment, suggesting that SH3YL1 may not serve as a universal marker for cisplatin-induced AKI in this cohort." (PMID 40362200, 2025).
chronic kidney disease (1 paper, 2023). Impairment of the renal function secondary to chronic kidney damage persisting for three or more months. "The levels of the urinary SH3YL1-to-creatinine ratio (USCR) were significantly different among the five stages of chronic kidney disease (CKD) and the three groups, based on albuminuria levels." (PMID 37109492, 2023).
diabetes (1 paper, 2023). "Recent reports have shown that SH3YL1 is a regulator of NOX4 and is a biomarker in animal models and patients with diabetes." (PMID 37109492, 2023).
endometrial cancer (1 paper, 2019). Primary or metastatic malignant neoplasm involving the endometrium (mucous membrane that lines the endometrial cavity). "SH3YL1 expression was considerably in endometrial cancer tissues compared with inactive endometrium." (PMID 30813939, 2019).
endometrioid tumor (1 paper, 2019). A benign, borderline, or malignant epithelial tumor of the female reproductive system characterized by the presence of glands and/or cysts lined by neoplastic cells that resemble endometrial cells. "ANO1, SOX17, CGNL1, DACH1, RUNDC3B, SH3YL1 and CRISPLD1 were significantly downregulated both in papillary serous tumors and endometrioid tumor." (PMID 30813939, 2019).
Hydrocephalus (1 paper, 2020). Hydrocephalus is an active distension of the ventricular system of the brain resulting from inadequate passage of CSF from its point of production within the cerebral ventricles to its point of absorption into the systemic circulation. "Amongst these, the SH3YL1 gene (related to cellular migration) and the SOCS7 gene (related to hydrocephalus in mice) are involved in CNS development." (PMID 32879369, 2020).
kidney injury (1 paper, 2025). Trauma to the kidney. "This elevation in baseline SH3YL1 levels in patients, irrespective of acute treatment response, suggests that SH3YL1 may reflect the underlying chronic pathology associated with MIBC rather than serve as an immediate marker for cisplatin-induced acute kidney injury." (PMID 40362200, 2025).
prostate carcinoma (1 paper, 2019). A carcinoma that arises from epithelial cells of the prostate gland. "Many coregulators of hormonal receptor have been identified and Src homology 3 domain containing, Ysc84-like 1 (SH3YL1) is a novel coregulator that bind to the polyproline domain of androgen receptor (AR) in prostate cancer cell." (PMID 30813939, 2019).
sarcoidosis (1 paper, 2022). Sarcoidosis is a multisystemic disorder of unknown cause characterized by the formation of immune granulomas in involved organs. "Further experiments need to elucidate the role of SH3YL1 in sarcoidosis." (PMID 35048206, 2022).
tumor (3 papers, 2014 to 2025). "Two of these, GSTP1 and SPINT2 were previously reported tumor suppressor genes which were hypermethylated in tumors with corresponding down-regulated gene expression, while the other 2 (CYB5R2 and SH3YL1) represent potential novel tumor suppressor genes." (PMID 25093504, 2014). "Functional network and Gene Ontology (GO) enrichment analyses identified SH3YL1’s interactions with NADPH oxidase pathways, particularly NOX family genes, and highlighted its roles in cell adhesion, migration, and cytoskeletal organization—processes critical for tumor invasiveness." (PMID 40362200, 2025).
cancer (2 papers, 2021 to 2025). A tumor composed of atypical neoplastic, often pleomorphic cells that invade other tissues. "Spearman’s correlation analysis revealed distinct patterns of association between the SH3YL1 and NOX family genes in NMIBC and MIBC, suggesting potential shifts in oxidative stress regulatory mechanisms during cancer progression." (PMID 40362200, 2025). "These additional studies could better elucidate the specific roles of SH3YL1 in cancer progression and its interactions with NOX family members." (PMID 40362200, 2025). "In addition to 4 same genes (KIAA0090, ATAD3B, TRIM27 and DMTF1) with LUSC-C1, ACP1 and SH3YL1 also played important roles in cancer." (PMID 33549049, 2021). "This suggests that SH3YL1 and NOX4 may act cooperatively in MIBC, potentially contributing to the invasiveness of cancer cells through enhanced oxidative stress modulation." (PMID 40362200, 2025).
kidney diseases (2 papers, 2023). "Considering the link between SH3YL1 and NOX4, it is necessary to confirm the significance of this biomarker in kidney diseases, in addition to detecting its level in various tissues, including the kidney." (PMID 37109492, 2023).
SH3YL1 also shares sentences with these, for which no sentence is quoted: cataract (1 paper); Nephropathy (1); Obesity (1); pediatric cancer (1); renal failure (1); schizophrenia (1).